SASH1 (SAM and SH3 domain containing 1)
Diseases named in the same sentence as SASH1 in open-access papers (continued):
Sharing a sentence is not in itself a finding about the gene and the disease.
tumor (continued). "Interestingly, several studies have reported that SASH1 plays an important role in promoting tumor cell invasion 10,12." (PMID 32174800, 2020). "In tumor cells, SASH1 has a significant effect on cell invasion." (PMID 33134379, 2020). "As SASH1 is a tumor suppressor, SASH1 knockdown could decrease β8 integrin expression, resulting in a decrease in cell adhesion." (PMID 31138780, 2019). "Recently, SASH1 was reported to be an inhibitor of tumor metastasis." (PMID 31138780, 2019). "SASH1, originally identified as a candidate tumour suppressor gene in breast and colon cancer, regulates the adhesive and migratory behaviours of cancer cells during tumour formation." (PMID 28382689, 2017). "The peak genome-wide significant pan-cancer DMP at cg02444695 upstream of the SASH1 tumour suppressor gene, showed consistently higher DNA methylation in the cancer-affected compared to their healthy co-twins, on average 0.7 % (range −0.9 to 3.0 % in normalised unadjusted DNA methylation levels)." (PMID 26798410, 2016). "In cancer, SASH1 is reported to function as a putative tumour suppressor." (PMID 27831555, 2016). "SAM and SH3 domain containing 1 (SASH1) is a putative tumour suppressor gene." (PMID 27831555, 2016). "The putative tumour suppressor, SASH1 (SAM and SH3 domain containing protein 1), has been previously implicated in the regulation of apoptosis; however, the molecular role of SASH1 in this process is still unclear." (PMID 27831555, 2016). "Accordingly, drugs that target NF-κB might be an effective strategy to target tumours with low SASH1 levels." (PMID 27831555, 2016). "Existing studies have indicated that SASH1 is a tumor suppressor." (PMID 26424902, 2015). "With advancing tumor stage, SASH1 mRNA expression decreased." (PMID 26424902, 2015). "However, as a tumor suppressor gene, the roles of SASH1 in normal astrocytes on controlling cell signaling require further investigation." (PMID 26424902, 2015). "Similarly, SAM and SH3 domain-containing protein (SASH1) is suggested to have a tumor suppression function." (PMID 20104256, 2010). "Interestingly, SASH1 expression was significantly downregulated in invasive and metastasised tumours." (PMID 17088907, 2006). "Downregulation of SASH1 protein was detectable in eight out of 10 tested tumours." (PMID 17088907, 2006). "Alternatively, the downregulation of SASH1 in tumours may be explained by genetic mechanisms such as LOH or point mutations." (PMID 17088907, 2006). "Therefore, SASH1 may be a critical molecular node whose expression status links the intrinsic malignant transformation of tumor cells with the pro-tumorigenic remodeling of the extrinsic microenvironment." (PMID 41099090, 2025). "Due to the well-established correlation of both EphA2 and SASH1 with tumor onset and progression, herein, to investigate how/if the formation of the SASH1-Sam1/EphA2-Sam complex could affect EphA2 activities in cancer, we focused on cancer-linked mutations in SASH1-Sam1." (PMID 39942820, 2025). "Notably, EFHD1 and SLC25A18 exhibited strong positive correlations with cellular processes related to the cell cycle (Cor = 0.368/0.385, P < =0.001), whereas SASH1 and FAM110B were found to be closely associated with tumor stemness (Cor =0.328/0.427, P < =0.001)." (PMID 40018519, 2025). "While there is a slightly higher tumor mutational burden in EPAS1-altered tumors (9.9 vs. 4.9 mut/Mb), they are enriched in and associated with genes promoting immune evasion, including ARID5B, SPINT1, AAK1, CLIC3, SORT1, SASH1, and FGFR3, respectively (q < 0.001)." (PMID 36421334, 2022). "In addition, the overexpression of miR‐130b enhanced tumour growth in vivo by suppressing SASH1." (PMID 30443973, 2019). "Therefore, the molecular context and tumor stage may significantly contribute to the biology of SASH1, which may extend beyond tumor suppression." (PMID 30340556, 2018).
tumor (continued). "Thus although SASH1 has been coined a tumour suppressor, our findings suggest that this may be oversimplifying its role and that context is critical." (PMID 27637080, 2016). "Indeed, SASH1 expression was clearly downregulated in liver metastasis, and the expression levels in the metastases were equal to or lower than the expression in the primary tumour from the same patient." (PMID 17088907, 2006). "COL1A1 and EMP1 were significantly upregulated in tumor tissues, while MYH11 and SASH1 were significantly downregulated." (PMID 41099090, 2025). "The SAM and SH3 domain-containing 1 (SASH1) overexpression significantly inhibited cell invasion and proliferation by downregulation of MMP-2 and MMP-9, suggesting its tumor-suppresive role via the FAK-related axis." (PMID 41148856, 2025). "In striking contrast to SASH1, the expression of COL1A1 clearly delineated the stromal architecture of the tumor." (PMID 41099090, 2025). "Some of the interesting genes among these include—SASH1 (SAM and SH3 domain containing 1), a potential tumor suppressor with negative regulation of proliferation, and invasion of cancer cells." (PMID 37641095, 2023). "MiR-130b-3p has been determined to target multiple tumor suppressors, such as PTEN, HOXA5, and SASH1, in various types of cancer, resulting in cancer progression and treatment resistance." (PMID 36217202, 2022). "SASH1 (SAM and SH3 domain containing 1) is a newly discovered scaffold protein, which is considered as a tumor inhibitor." (PMID 26424902, 2015). "Many recent studies have shown that SASH1 is ubiquitously expressed in most normal tissues but is decreased or absent in tumor tissues, supporting its function as a tumor inhibitory gene." (PMID 36286186, 2023). "SAM and SH3 domain-containing 1 (SASH1), a scaffold protein, is regarded as a tumor suppressor." (PMID 31138780, 2019). "To explain how miR‐9 may possibly regulate the tumorigenic potential of HNSCC cells, we first looked to the oncosuppressor SASH1 that we previously showed to be a bona fide miR‐9 target in HNSCC and has been involved in the regulation of EMT in different tumor types, including cutaneous SCC." (PMID 34062049, 2021). "Therefore, it is tempting to speculate that SASH1 does not play a role in the early phases of tumour initiation, but is rather related to processes such as tumour invasion in the surrounding tissue, and dissemination of tumour cells to distant organs." (PMID 17088907, 2006). "However, SASH1 expression was not significantly correlated to the anatomical tumour site." (PMID 17088907, 2006). "Among the 23 HERV-derived miRNAs, hsa-miR-4454, which is derived from the HERV-H family, showed oncogenic traits by targeting the two tumor suppressor genes, DNAJB4 and SASH1, in non-muscle-invasive bladder cancer (NMIBC)." (PMID 38002927, 2023). "The mRNA levels of RBL2 (P=0.2687), SASH1 (P=0.0859), S100A8 (P=0.2198) and S100A9 (P=0.0731) were not significantly different between ER+-cancer tissues and ER+-tumor-adjacent tissues." (PMID 29416786, 2018). "SASH1 depletion in HBEC cells did not affect sensitivity to cisplatin, indicating this effect may be specifc to tumour cells." (PMID 33122723, 2020).
cancer (26 papers, 2006 to 2025). A tumor composed of atypical neoplastic, often pleomorphic cells that invade other tissues. "Of course, experimental validation and in vitro assays in diverse cancer cell lines are needed to undoubtedly associate antioncogenic effects with the EphA2-Sam/SASH1-Sam1 complex." (PMID 39942820, 2025). "Following our approach, we first searched the COSMIC catalogue for cancer-related missense mutations in the SASH1-Sam1 domain." (PMID 39942820, 2025). "We employed a computational strategy to analyze cancer-related mutations in the first Sam domain of the adaptor protein SASH1 from a structural point of view." (PMID 39942820, 2025). "Expression of the SASH1 protein is reduced in a range of human cancers and has been implicated in apoptotic cancer cell death." (PMID 27637080, 2016). "Further studies with the Haddock refinement interface were next carried out to verify how a few selected cancer-related mutations could affect the binding of EphA2-Sam to SASH1-Sam1." (PMID 39942820, 2025). "Specifically, SASH1-deficient cancer cells may, through paracrine mechanisms such as secreting cytokines like TGF-β, activate adjacent fibroblasts, inducing their transformation into pro-tumorigenic cancer-associated fibroblasts (CAFs)." (PMID 41099090, 2025). "Thus, herein, to investigate a possible correlation between the formation of the SASH1-Sam1/EphA2-Sam complex and EphA2 activity in cancer, cancer-linked mutations in SASH1-Sam1 were deeply analyzed." (PMID 39942820, 2025). "In the end, this preliminary computational study highlights that the relationship to cancer of certain SASH1-Sam1 mutations (like the Y659C and D661H) could be due to negative modulation of the SASH1-Sam1/EphA2-Sam association." (PMID 39942820, 2025). "Studying the EphA2-Sam/SASH1-Sam1 complex in the context of SASH1-Sam1 cancer-related variants could provide important insights for applications in the anticancer drug discovery field." (PMID 39942820, 2025). "Next, through docking studies, with the support of Haddock and AF2 structure predictions, we investigate if/how cancer-linked mutations in SASH1-Sam1 could affect binding to EphA2-Sam." (PMID 39942820, 2025). "Then, 3D models of different cancer-related SASH1-Sam1 variants were built with AF2." (PMID 39942820, 2025). "Even though SASH1 was globally down-regulated among all tumors and its expression associated with favorable prognosis, certain subgroups like estrogen receptor positive cancers showed a significantly reduced survival for cases with high SASH1 expression." (PMID 30340556, 2018). "SASH1 downregulation in different cancer types correlates with decreased patient survival and enhanced formation of metastasis, probably due to its pro-apoptotic activity and the capacity to block EMT (epithelial–mesenchymal transition)." (PMID 39942820, 2025). "In fact, SASH1 is a known tumor suppressor protein, whereas EphA2, although exhibiting often controversial functions, is associated with several pro-cancer activities; thus, this Sam–Sam interaction could be important to modulate the EphA2 cancer-related signaling pathway." (PMID 39942820, 2025). "Our computational study suggested that a few cancer-related SASH1-Sam1 variants, with mutations inside the ML interface (i.e., L667P and Y659C), could more likely disturb the Sam1 domain fold and consequently avoid interaction between EphA2-Sam and SASH1-Sam1 through a kind of indirect mechanism." (PMID 39942820, 2025). "SAM1 is found to be part of the region important for SASH1’s function in regulating cytoskeleton reorganization in cancer cells." (PMID 37296980, 2023). "We have found significant genes (SASH1, TBX2, HBEGF, etc.)linked to NSCLC cancer that can serve as potential drug targets." (PMID 37324026, 2023). "Specifically, both SASH1 and Liprins can regulate these functions in various cancer cell types, likely through modulating proteins involved in cytoskeleton organization." (PMID 37296980, 2023).
cancer (continued). "In support of this, our study has demonstrated that SASH1 does function within the cancer phenotype, with a prominent role in apoptosis." (PMID 33122723, 2020). "The further investigation of the mechanism by which chloropyramine increases SASH1 level will allow the development of new-targeted agents to increase the efficacy of targeting SASH1 as a cancer therapy." (PMID 33122723, 2020). "MiR‐130b and SAM and SH3 domain containing 1 (SASH1) play an important role in many types of human cancers." (PMID 30443973, 2019). "Transfecting the three most sensitive lines with SASH1 siRNA prior to treatment partially rescued the cytotoxic response, suggesting that chloropyramine-induced cancer cell line death is at least partly mediated by SASH1." (PMID 27637080, 2016). "The greatest DNA methylation difference at the top-ranked probe (cg02444695 near SASH1) between the MZ twin-pairs was observed when the DNA sample was obtained earlier in the same year as cancer diagnosis." (PMID 26798410, 2016). "The precise molecular functions of SASH1 in normal tissues and cancer are still being investigated, though it is known to localise to the nucleus, and its SAM and SH3 domains imply signalling, adaptor and/or molecular scaffold functions." (PMID 27637080, 2016). "Our previous most-associated pan-cancer DMP (cg02444695 near SASH1 in 41 MZ pairs) remained strongly significant (P = 2.40 × 10−5) and with the same direction of association in the new EWAS prior to cancer diagnosis, and was now ranked tenth overall." (PMID 26798410, 2016). "Forty-two per cent of all carcinomas (48 out of 113 samples) showed SASH1 expression that was 10-fold lower in comparison to normal colon tissue." (PMID 17088907, 2006). "SASH1 has been related to diverse pathological conditions, including atherosclerosis and dermatological pathologies, but it has been widely investigated in the framework of human cancer." (PMID 39942820, 2025). "Second, in maintaining tissue architecture, SASH1 positively regulates “cell adhesion”, including cell-cell junctions and cell-matrix adhesion, to preserve epithelial integrity and thus limit cancer cell invasion and metastasis." (PMID 41099090, 2025). "Currently, the functional meaning of the SASH1-Sam1/EphA2-Sam complex is unknown, but EphA2 is a well-established and crucial player in cancer onset and progression." (PMID 39942820, 2025). "In cancer cells, SASH1 can inhibit proliferation, migration, and metastasis." (PMID 37296980, 2023). "Second, SASH1 was the strongest TS gene acting on gene up-expression in cancer." (PMID 33580150, 2021). "Previously, we hypothesised that pharmacologically increasing SASH1 levels may be a novel approach to cancer therapy." (PMID 33122723, 2020). "SASH1 has been identified as a candidate tumor suppressor gene in several cancers 7-9." (PMID 32174800, 2020). "SASH1 plays an important role in cancer initiation, development, and metastasis." (PMID 30443973, 2019). "In this study we used in silico connectivity mapping and in vitro modelling to identify drugs that could be repositioned to augment SASH1 expression in cancer." (PMID 27637080, 2016). "Therefore, it was reasonable to hypothesize that missense mutations of SASH1 and WASF3 might cause target gene mutations of anticancer drugs in LUAD, thereby causing drug resistance in cancer cells." (PMID 37322027, 2023). "These suggest that RAP1A, STARD13, SASH1, RECK, and CBFA2T3 had big positive network effects on down-expression of genes in stage-3 cancer." (PMID 33580150, 2021). "D ifferential expression analysis revealed that SASH1 is downregulated in NSCLC, which may be a factor leading to cancer progression." (PMID 37324026, 2023). "In vitro studies with cancer cells show that SASH1 protein inhibits migration, invasion, and epithelial-mesenchymal transition (EMT), decreases cell proliferation and survival, or promotes apoptosis in breast, colon, melanoma, and many other cancer types." (PMID 37296980, 2023).
cancer (continued). "At stage 3, STARD13, CBFA2T3, RECK, and SASH1 had strong accordant/discordant effects on expression of genes in cancer, while APC, EXT1, NBL, KLK10, and PTCH1 had very weak accordant/discordant impacts on expression of genes in cancer." (PMID 33580150, 2021). "Hence, the strong TS genes SASH1, STARD13, RECK, CBFA2T3, RASSF2, RAP1A, and ARHGEF12 can be used as specific biomarkers for diagnosis of NSCLC cancer." (PMID 33580150, 2021). "SASH1 localises to the nucleus, and its SAM and SH3 domains imply signalling, adaptor and/or molecular scaffold functions, although the precise molecular functions of SASH1 in normal tissues and cancer remain to be fully elucidated." (PMID 33122723, 2020). "However, the predictive capacity of SASH1 deregulation in human cancer has not been determined previously." (PMID 17088907, 2006).
adenocarcinoma (2 papers, 2020 to 2023). A common cancer characterized by the presence of malignant glandular cells. "Here, we show that low SASH1 mRNA expression is associated with poor survival in adenocarcinoma." (PMID 33122723, 2020).
infection (2 papers, 2021 to 2022). The state of being infected such as from the introduction of a foreign agent such as serum, vaccine, antigenic substance or organism. "SASH1 in locus 6q24.3-q25.1 encodes a scaffold protein, which stimulates cytokine production through NF-κB signaling pathway and facilitate endothelial responses to inflammation/infection." (PMID 35999196, 2022). "These loci exhibited negative (ELN, SASH1, and SMAD7) and positive (CDSN, NCSTN, and PEX7) relationships between minor allele frequency and infection severity, with no overarching pattern evident in control loci lacking association with mange severity." (PMID 33664786, 2021).
mitochondrial disease (1 paper, 2025). "The identification of mitochondrial disease-specific markers (EFHD1, SASH1, FAM110B, and SLC25A18) highlights shared mechanisms, such as oxidative phosphorylation, calcium signaling, and immune responses, that can serve as therapeutic targets in both AD and GBM." (PMID 40018519, 2025).
SASH1 also shares sentences with these, for which no sentence is quoted: gastric cancer (7 papers); Palmoplantar keratoderma (5); cervical cancer (4); genodermatosis (3); skin carcinoma (3); ganglioneuroblastoma (2); thyroid cancer (2); alopecia (1); coloboma (1); colorectal tumours (1); cutis laxa (1); deafness (1); esophageal squamous cell carcinoma (1); head and neck squamous cell carcinoma (1); hearing loss (1); hidradenitis suppurativa (1); Huriez syndrome (1); Hyperkeratosis (1); hyperplasia (1); hypothyroidism (1); keratitis (1); major depression (1); mood disorder (1); Olmsted syndrome (1); ovarian carcinoma (1); peripheral neuropathy (1); prostate carcinoma (1); psoriasis (1); psychiatric disorder (1); skin pigmentation disorder (1).
A further 2 diseases each share a sentence with SASH1 in 1 paper.